ACE (angiotensin I converting enzyme)
Diseases named in the same sentence as ACE in open-access papers (continued):
Sharing a sentence is not in itself a finding about the gene and the disease.
melanoma (continued). "Therefore, the effect of Ang-II/ACE on nuclear Ca2+ signaling might explain the observed Ang-II’s action as a mitogen, in the melanoma cell line (TM-5), a murine cell type that endogenously expresses ACE, but lack Ang-II type 1 or type 2 receptors." (PMID 27992423, 2016). "To further investigate the role of ACE on cell proliferation, we used the murine melanoma cells (TM-5), since TM-5 cells endogenously express ACE, but do not express AT1 and AT2 receptors." (PMID 27992423, 2016). "In conclusion, ACE has been proved to possess antimelanoma and antioxidant properties, being able to prevent melanoma cell growth and migration through the regulation of the main proteins involved in EMT and angiogenesis, and perturbing the melanoma cells cytoskeleton organization." (PMID 36010420, 2022). "However, the function that ACE plays as an Ang-II receptor in melanoma cells has not been defined yet." (PMID 27992423, 2016).
pulmonary sarcoidosis (12 papers, 2016 to 2026). Sarcoidosis affecting the lung parenchyma. "Serum concentrations of IL-12 p40 have been found significantly higher in pulmonary sarcoidosis than healthy subjects and have been correlated with serum levels of ACE and lysozyme." (PMID 26879979, 2016). "Previous studies have demonstrated the correlations of serum levels of inflammatory chemokines and cytokines with serum ACE and lysozyme activities in patients with ocular and pulmonary sarcoidosis." (PMID 26879979, 2016). "A cross-sectional study in China showed that the serum ACE level in patients with pulmonary sarcoidosis concomitant extrapulmonary involvement was higher than that in patients with isolated pulmonary sarcoidosis, and was related to extrapulmonary organ involvement and overall disease activity." (PMID 37868968, 2023). "Serum ACE is elevated in some patients with pulmonary sarcoidosis, and this parameter can be valuable for diagnosis; however, ACE dynamics may not completely reflect the treatment status." (PMID 26845566, 2016).
Ventricular arrhythmia (12 papers, 2016 to 2025). "A large retrospective study demonstrated that beta blockers and ACE inhibitors are associated with improved secondary survival in patients surviving ventricular arrhythmias on admission." (PMID 32565909, 2020). "There was ahighly significant relationship between NOx levels and gender(p = 3.13e-06), creatinine(p = 3.96e-15), ventricular arrhythmia(p = 9.49e-05), ACE inhibitors(p = 4.23e-05), and the interactionbetween ACE inhibitors and HDL(p = 4.30e-05)." (PMID 29257712, 2018). "He underwent endotrachealintubation and developed septic and cardiogenic shock and ventricular arrhythmias.He was treated with benznidazole, Angiotensin Converting Enzyme (ACE) inhibitors,beta-blockers, vasoactive amines, ceftriaxone and amiodarone." (PMID 27533369, 2016). "Moreover, a study indicated that cardiac-specific ACE overexpression in mice resulted in changes in connexins consistent with the phenotype of low-voltage electrical activity, conduction defects, induced ventricular arrhythmia, and higher cardiogenic mortality." (PMID 36311192, 2022). "Other studies evaluating baseline predictors of ventricular arrhythmias in a CRT population found variable results but identified gender, no beta-blocker or ACE inhibitor use, severely decreased LVEF and NYHA class IV as predictors of ventricular arrhythmias." (PMID 26797979, 2016).
Autoimmunity (11 papers, 2019 to 2025). The occurrence of an immune reaction against the organism's own cells or tissues. "Studies have revealed the presence of a local renin–angiotensin system in the skin, where the angiotensin-converting enzyme (ACE) is involved in autoimmunity and causes alopecia due to HF’s chronic inflammation." (PMID 37763773, 2023). "Baseline levels of ACE and ACE 2 appear to be associated with disease activity, inflammatory markers such as ESR, and indicators of autoimmunity like RF." (PMID 41010368, 2025). "Baseline ACE and ACE2 might be associated with disease duration, markers of inflammation (ESR), and autoimmunity (RF)." (PMID 37877017, 2023). "Significant triggers other than autoimmunity for PR can be bacterial, viral, environmental factors like seasonal change, atopy, stress, or drugs such as ACE inhibitors, like captopril, Allopurinol, hydrochlorothiazide, barbiturates, nimesulide, and metronidazole." (PMID 37102660, 2023). "Baseline ACE and ACE2 may be associated with disease duration, markers of inflammation (CRP), autoimmunity (RF) and vascular pathophysiology (FMD, IMT)." (PMID 35155468, 2021). "Thus, in JAKi-treated RA patients exerting low-grade inflammation, ACE levels might serve as a marker of autoimmunity (RF)." (PMID 37877017, 2023). "ACE inhibitor treatment has not been associated with autoimmunity in humans to date." (PMID 36016727, 2022).
benign prostatic hypertrophy (11 papers, 2011 to 2024). "As far as the community-dwelling prescriptions are concerned, the most frequent pair was ACE-inhibitors—NSAIDs (7.2%), followed by calcium channel blockers—α-blockers (2.4%; including both antihypertensive and drugs used in benign prostatic hypertrophy) and by antidiabetics—beta-blockers (2.3%)." (PMID 33628186, 2020).
cardiac arrest (11 papers, 2012 to 2026). Cessation of breathing and/or cardiac function. "cardiac arrest, and the ACE DD genotype was found to confer an increased risk of diastolic heart failure, ACS recurrence and cardiovascular mortality, although controversial and negative results have also been reported." (PMID 22333273, 2012). "Ang II has not been described specifically for cardiac arrest, but a 2016 porcine cardiac arrest study examined Ang II levels with and without ACE inhibitor pretreatment." (PMID 29282149, 2017).
colitis (11 papers, 2014 to 2026). Inflammation of the colon. "ACE inhibitor treatment was also effective in spontaneous colitis of IL-10-deficient mice and this finding has been confirmed by other studies." (PMID 24678903, 2014). "Treatment of mice with inhibitors of Angiotensin-converting enzyme (ACE) or Angiotensin II (AngII) receptor type 1 (AT1R) prevented the colitis-induced atrial electrophysiological remodeling." (PMID 40723857, 2025). "ACE-Is prevented the generation of proinflammatory cytokines in mouse models of colitis and colonic fibrosis, most likely through inhibiting the TGF-β signaling pathway, paving the way for an innovative inflammatory bowel disease treatment." (PMID 37509613, 2023). "In vivo administration of the ACE inhibitor enalaprilate has been proven to reduce weight loss and histological damage in murine dextran sulfate sodium (DSS)-induced colitis." (PMID 24678903, 2014). "Furthermore, MLP is recognized for its high nutritional value, excellent functional properties, and diverse bioactivities, including antioxidant effects, blood sugar reduction, cholesterol-lowering, colitis alleviation, and ACE inhibitory activity." (PMID 40807539, 2025). "An increase in angiotensinogen (Agt) expression during colitis could therefore occur through increased sympathetic signaling, inflammatory cytokines, increased renin secretion through reduced SCFAs, and enhanced ACE and AngII receptor type 1 (AT1R) signaling through LPS." (PMID 40723857, 2025). "The colitis mice demonstrated reduced Chao1, angiotensin-converting enzyme (ACE), and Shannon indices and an increased Simpson index, but the colitis mice receiving dietary Q or Q+MQ exhibited higher Chao1, ACE, and Shannon indices and a reduced Simpson index." (PMID 30539022, 2018). "The remodeling of the conduction velocity and APD could be prevented by treatment of mice with i(ACE) or i(AT1R) during the induction of colitis." (PMID 40723857, 2025).
erectile dysfunction (11 papers, 2015 to 2026). Persistent or recurrent inability to achieve or to maintain an erection during sexual activity. "Increase in the angiotensin-I converting enzyme (ACE) caused by erectile dysfunction simultaneously leads to the generation of angiotensin-II." (PMID 30890127, 2019). "Furthermore, CO hydrosol was evaluated against enzymes associated with erectile dysfunction, namely acetylcholinesterase (AChE), angiotensin-I converting enzyme (ACE), and arginase type 2 (ARG2)." (PMID 38891326, 2024). "The antioxidant properties and ACE and arginase inhibitory effects of phenolic extract from M. oleifera leaves suggest that this plant has a therapeutic potential in the management of erectile dysfunction." (PMID 26557995, 2015). "Application: prospects for development of an additive or ingredient for natural remedy for erectile dysfunction;Extraction procedure: SD;Chemical composition: GC–MS;Biological characterisation: PDE5, ACE, AChE, and ARG2 inhibition assays." (PMID 39407589, 2024). "Both MR and RCTs showed ACE inhibitors, BBs and CCBs were unlikely to exert effects on COVID-19 outcomes or erectile dysfunction." (PMID 39567981, 2024). "The phenolic contents, inhibition of ACE, arginase, and Fe2+-induced MDA production, and radical (OH∗, NO∗) scavenging and Fe2+-chelating abilities could be some of the possible mechanisms by which M. oleifera leaves could be used in the treatment and/or management of erectile dysfunction." (PMID 26557995, 2015).
glomerulonephritis (11 papers, 2002 to 2025). A renal disorder characterized by damage in the glomeruli. "Further diseases linked to PPROM were nephritis or glomerulonephritis (ACE, COL4A3, COL4A4, IGF1, NOS2, REN, TNF)." (PMID 25264875, 2014). "Material collection was performed before starting treatment with ACE inhibitors, the standard treatment for patients with proteinuria and glomerulonephritis." (PMID 40364208, 2025). "ACE inhibitors are the standard treatment for patients with proteinuria and glomerulonephritis." (PMID 39768675, 2024).
hepatocellular carcinoma (11 papers, 2013 to 2025). A malignant tumor that arises from hepatocytes. "Previous meta-analysis showed that the ACE I/D polymorphism is associated with hepatocellular carcinoma (HCC), indicating that this polymorphism contributes to HCC progression in the Chinese population." (PMID 25889770, 2015). "Between 2004 and 2006, a 48-month follow up study was conducted on 89 patients with cirrhosis associated with hepatocellular carcinoma (HCC) in Japan using combination therapy with branched-chain amino acid (BCAA) granules and an ACE inhibitor, perindopril." (PMID 33670126, 2021). "Using a murine hepatocellular carcinoma development model, Yoshiji and colleagues showed that combination therapy based on an angiotensin-converting enzyme (ACE) inhibitor (Perindopril [PE]) was able to inhibit angiogenesis mediated by VEGF overexpression." (PMID 24391821, 2013). "The interaction between Angiotensin II (AngII) and angiotensin type 1 receptor (AT1R) may have a pivotal role in hepatocellular carcinoma (HCC) and therefore, AT1R blocker and angiotensin I-converting enzyme (ACE) inhibitors may have therapeutic potential in the treatment of hepatic cancer." (PMID 24391821, 2013).
influenza (11 papers, 2017 to 2024). An acute viral infection of the respiratory tract, occurring in isolated cases, in epidemics, or in pandemics; it is caused by serologically different strains of viruses (influenzaviruses) designated A, B, and C, has a 3-day incubation period, and usually lasts for 3 to 10 days. "Interestingly, a study of electronic health records of patients in the Clinical Practice Research Datalink in the United Kingdom showed a lower risk of influenza infection depending on the duration of ACE inhibitor use." (PMID 38275965, 2024). "Ramipril is an inhibitor of the angiotensin-converting enzyme (ACE), and a recent study found that individuals who have prescriptions for ACE inhibitors had a lower risk of influenza." (PMID 38275965, 2024).
leukemia (11 papers, 1980 to 2024). A malignant (clonal) hematologic disorder, involving hematopoietic stem cells and characterized by the presence of primitive or atypical myeloid or lymphoid cells in the bone marrow and the blood. "The phenolic extracts were found to inhibit proliferation of cancer cells and specifically induce apoptosis in leukaemia cells while inhibiting angiotensin-converting-enzyme (ACE), α-glucosidase and pancreatic lipase." (PMID 30081504, 2018). "ACE inhibitors, as well as Ang II receptor blockers such as losartan, inhibited cell growth, decreased c-myc expression and increased apoptosis in leukemia cell lines." (PMID 28209920, 2017).
malnutrition (11 papers, 2014 to 2024). Inadequate nutrition resulting from poor diet, malabsorption, or abnormal nutrient distribution. "Furthermore, some medications, such as angiotensin-converting enzyme inhibitors (ACE), can impair kidneys development Maternal malnutrition and a low-protein diet during pregnancy can have a detrimental impact on the developing kidneys system." (PMID 39076761, 2024).
aspiration pneumonia (10 papers, 2013 to 2025). "Among the 22 patients undergoing antihypertensive therapy, only 2 were prescribed ACE inhibitors, which enhance substance P levels and improve cough reflex sensitivity, reducing aspiration pneumonia risk in elderly patients." (PMID 40764950, 2025). "The patient’s treatment plan upon discharge included antibiotics for acute aspirational pneumonia, alongside antihypertensive therapy combining beta-blockers and Angiotensin-Converting Enzyme (ACE) inhibitors." (PMID 40641529, 2025).
coronary atherosclerosis (10 papers, 2010 to 2024). Atherosclerosis of the coronary vasculature. "An earlier study showed that the ApoE ε4 allele is associated with coronary atherosclerosis in AD patients due to the emergence of the angiotensin-converting enzyme DD genotype (ACE-DD), which is increased as the patient ages." (PMID 35011591, 2021). "It has also been shown that ACE inhibitor use significantly reduces coronary atherosclerosis." (PMID 39080618, 2024). "This has been supported by the evidence of the efficacy of angiotensin-converting enzyme (ACE) inhibitors and angiotensin-II receptor blockers (ARBs) in halting the development of coronary atherosclerosis and related coronary events." (PMID 25984491, 2014). "Patients with multi-vessel CAD were treated more extensively with acetylsalicylic acid, beta blockers and ACE inhibitors than those without coronary atherosclerosis." (PMID 23512577, 2013). "The SCAT (Simvastatin/Enalapril Coronary Atherosclerosis Trial) and PREVEND IT (Prevention of Renal and Vascular Endstage Disease Intervention Trial) trials were placebo-controlled randomized clinical trials with a 2 × 2 factorial design to study the combined effects of ACE inhibitors and statins." (PMID 36194352, 2024).
Cough (10 papers, 2009 to 2025). A sudden, audible expulsion of air from the lungs through a partially closed glottis, preceded by inhalation. "A previous study showed that Chinese patients had a notably higher risk of ACE inhibitor-related cough than Caucasians29." (PMID 33976340, 2021). "Association of SLCO1B1 genetic polymorphisms with the risk of ACE-Is-induced cough." (PMID 39295941, 2024). "This supported the notion that the ACE I/D polymorphism was associated with ACEI-related cough." (PMID 22723835, 2012). "We found that the I allele of the ACE gene increased the susceptibility to ACEI-related cough." (PMID 22723835, 2012). "In their meta-analyses, the ACE I/D polymorphism was associated with ACEI-related cough in Asians." (PMID 22723835, 2012). "After adjustment, patients with H4 were 22 times more likely to have the ACE inhibitor-induced cough." (PMID 39295941, 2024). "Other studies reported similar frequencies of ACE inhibitor-induced cough in the Malaysian and Chinse populations (24.1% and 32% respectively)." (PMID 39295941, 2024). "It is effective for information retrieval methods on unstructured text to select patients with ACE inhibitor–related cough, as the keywords ACE inhibitor and cough usually co-occur in clinical text contexts as adverse drug events." (PMID 33021486, 2020). "Future investigations aimed at elucidating the age-dependence of the association between the ACE I/D polymorphism and ACEI-related cough may help to clarify the mechanism of ACEI-related cough." (PMID 22723835, 2012). "The role of ACE in the metabolism of bradykinin has been proposed as a pathogenic mechanism, and the effect of genetic polymorphisms in bradykinin receptors and ABO genes, related to ACE levels and associated with ACE-I-related cough, has been found more pronounced in women." (PMID 29804162, 2018). "This could have confounded the association between the ACE I/D polymorphism and ACEI-related cough." (PMID 22723835, 2012). "Bradykinin, a peptide degraded by ACE, has been suggested to play a major role in ACEI-related cough." (PMID 22723835, 2012).
epilepsy (10 papers, 2008 to 2024). A brain disorder characterized by episodes of abnormally increased neuronal discharge resulting in transient episodes of sensory or motor neurological dysfunction, or psychic dysfunction. "The induced epilepsy in this study was characterized by an increased expression of Ang II and a reduced expression of ACE in all phases." (PMID 30744022, 2019). "Therefore, studying the effects of ACE inhibitors on the C3-dependent glial activation is of great significance for the clinical medication for epilepsy." (PMID 36104755, 2022). "Captopril, an angiotensinase inhibitor, was used in our study to demonstrate the potent effects against epilepsy and improving epilepsy-related cognitive dysfunction, which can be considered a potential drug candidate for treating epilepsy by targeting the ACE." (PMID 36104755, 2022). "RAS involvement in epilepsy pathology is associated with the hyperactivation of Ang II/ATR1 and ACE signaling in astrocytes, oligodendrocytes and microglia, and is induced by an increase in proinflammatory cytokines, macrophage activation, oxidative stress, and BBB dysfunction." (PMID 30744022, 2019). "Carbamazepine has also demonstrated inhibitory action of the ACE enzyme in the hippocampus, which may be linked to the beneficial effects of RAS inhibition and its role with AEDs alone in epilepsy pathophysiology, characterized by increased RAS expression and activation." (PMID 30744022, 2019). "However, there have been few reports on the association of the renin receptor ACE and ATR1 in relation to mental disorders and epilepsy, suggesting a need for pharmacogenetic and genetic association studies targeting the RAS pathway in epilepsy." (PMID 30744022, 2019). "Our future research will focus on the effect of ACE or RAS on GABAergic interneurons, especially GABA release, in the epilepsy model, and examine its molecular mechanism." (PMID 35345815, 2022). "In genetic audiogenic models of epilepsy, Wistar audiogenic rats or DBA/2 mice treated with an AT1 blocker or ACE inhibitors show a significant decrease in seizure severity." (PMID 24705860, 2014). "In an audiogenic animal model of epilepsy, besides AT1, also angiotensin-converting enzyme (ACE) is upregulated in the brain following repetitive seizures." (PMID 24705860, 2014).